IFNG (interferon gamma)
Diseases named in the same sentence as IFNG in open-access papers (continued):
Sharing a sentence is not in itself a finding about the gene and the disease.
tumor (continued). "Compared to Kaede-red tumour emigrants in the dLN, CCR7+ DCs in tumours were enriched in ‘interferon gamma response’ genes." (PMID 38267413, 2024). "It has been reported that the tumor microenvironment of ACSL4−/− animal models displays decreased infiltration of CD8+, IFNγ+CD8+, TNFα+CD8+, and CD4+ T cells compared to the tumor microenvironment of ACSL4+/+ animal models." (PMID 38778030, 2024). "Inhibition of AhR restored the inflammatory phenotype of macrophages and promoted the infiltration of IFNγ+CD8+T cells, which weakened Ahr-dependent tumor growth." (PMID 38279145, 2024). "HSP60-KD reduced tumor volumes and weights and increased total CD4+ T cells and CD8+ T cells, including IFNγ+ CD8+ T cells and GZMB+ CD8+ T cells." (PMID 39256398, 2024). "The resulting T cells secreted IFNγ and exerted increased tumor‐specific cytolytic function relative to controls, demonstrating the versatility of PBNP‐PTT in generating tumor‐specific T cells for ATCT." (PMID 38818122, 2024). "Splenic cells from mice after complete tumor elimination by combination therapy were cultured in the presence of AH1 peptide for 1 week, and IFNγ-producing cells were assessed by ELISPOT assays." (PMID 39054418, 2024). "Increased clearance of Atg16l1 KO tumors by cytotoxic lymphocytes and IFNγ, along with a persistently enhanced IFN-response gene signature in NSG mice prompted us to directly characterize the role of tumor-intrinsic ATG16L1 in regulating IFNγ signaling." (PMID 37741832, 2023). "Specifically, BBL-28.mζ CAR T-cells released higher levels of IFNγ, IL2, and GMCSF at first and fourth stimulations with GL261 tumor cells (BBL-28.mζ vs. other constructs P < 0.05)." (PMID 37971169, 2023). "Moreover, they express effector molecules, which are destined to kill tumor cells, including perforin 1, granzyme B and TNFα, as well as multiple pro-inflammatory cytokines that are characteristic for activated macrophages and Th1 cells, including IL-1β, IL-6, IL-2 and IFNγ." (PMID 37174085, 2023). "Our multi-scale models show that Interferon gamma (IFNγ)-induced partial EMT of a tumor cell subpopulation can provide some, albeit limited protection to bystander tumor cells." (PMID 37638024, 2023). "Incubated with tumor cells SK‐BR‐3, the CAR‐T cells activated by FreeSwitch secreted more interferon‐gamma (IFN‐γ) than the inactivated CAR‐T cells (p < 0.001), indicating that the CAR‐T cells can be activated by switch." (PMID 36755195, 2023). "Chronic IFNγ signalling consistently induced expression of Qa-1b/HLA-E, a ligand for the cytotoxic lymphocyte inhibitory receptor NKG2a/CD94, in mouse tumour models, thereby conferring resistance to α-PD-1 therapy." (PMID 37752135, 2023). "In response to restimulation with the tumor-specific peptide, induction of the CD8+ T cell effector cytokine interferon gamma (IFN-γ) was greatly enhanced from splenocytes of CT26-bearing mice treated with an anti-TIGIT antibody with an intact Fc backbone." (PMID 38022590, 2023). "We noticed a significant induction of IFNγ and inhibin-A (INHBA) protein levels in serum of KPC-bearing mice compared to control, tumor-free mice." (PMID 37095087, 2023). "Coculture of BTICs with tumor reactive cytotoxic T cells or with T cell-derived factors induced TSPO up-regulation through T cell derived TNFα and IFNγ." (PMID 37158962, 2023). "As T cell cytotoxicity indicators, interferon gamma (IFNγ), and cytolytic granule enzyme Granzyme B (GZMB) had greater expression levels in the CD8 T cells of the tumor organoids when they were treated with ITF2357, I‐BET151, or JQ1." (PMID 37271874, 2023). "IFNγ is also well known for the induction of surface major histocompatibility complex (MHC) class I expression, thereby facilitating tumor cell recognition by cognate CD8+ T lymphocytes." (PMID 37650116, 2023). "More established immune markers need to be investigated, such as interferon-gamma, CTLA-4 and CD28, to further characterize the tumor immune microenvironment." (PMID 37175905, 2023).
tumor (continued). "Interferon-gamma (IFN-γ), classically considered as a pro-inflammatory cytokine, is expected to work as an anti-tumor agent." (PMID 38007483, 2023). "Meanwhile, evidence for the presence of IFNγ-producing CD4+ CTL in solid human cancers have been generated by single cell RNA sequencing and flow cytometry analyses of tumors and tumor infiltrates." (PMID 37965314, 2023). "The role of IFNG in GBM became more and more significant in recent years’ research, including GBM progression and the tumor immunosuppressive microenvironment." (PMID 37122693, 2023). "Anti-IFNγ blocked cisplatin-induced reduction in CD31+ tumour blood vascular density and the distribution of VE-cadherin on tumour vessels." (PMID 37056922, 2023). "CD4+ T cells can secrete cytokines, such as interferon-gamma (IFN-γ) and tumour necrosis factor-alpha (TNF-α), which directly kills tumour cells." (PMID 38130720, 2023). "In CD8+ T cells, decreased NFATC1 expression reduces IFNg production, whereas inhibiting lactate dehydrogenase A (LDHA) reduces intracellular acidification and restores CD8+ T cell function and tumor infiltration." (PMID 37842241, 2023). "IL-12 induces interferon gamma (IFN-γ) production, which in turn stimulates infiltration of cytotoxic T lymphocytes and natural killer cells (NK cells) into the tumour." (PMID 37629081, 2023). "Altogether, we observed that MSI CRC IFNG+CD8+ T cells have tumor-reactive exhaustion and stem-like progenitor signaling, while MSS CRC IFNG+CD8+ T cells showed heterogeneous inflammatory or tolerogenic features." (PMID 37968259, 2023). "TAS-115 is expected to exhibit both anti-angiogenesis activity and increase the percentage of active T cell populations, Gzmb+CD8+ T cells, IFNγ+CD8+ T cells, and MuLV+CD8+ T cells, relative to CD8+ T cells in tumor." (PMID 37258621, 2023). "In one study, tumors were stimulated with IFNg prior to culture with PBMCs and anti-PD1, and this process was repeated for several weeks to generate tumor-reactive T cells with a demonstrated killing capacity." (PMID 37190054, 2023). "The activated T cells secret IFNγ, enhancing GSDMB expression and establishing a positive feedback loop of T cell activation and tumor cell killing." (PMID 37587833, 2023). "Then, based on in vivo analysis and tumor specimen, we discovered the APOL3-LDHA axis can facilitate the tumor ferroptosis and cytotoxic ability of CD8+ T cells through increased IFNγ and decreased lactic acid concentration." (PMID 36923931, 2023). "To date, a variety of myokines has been identified, including main driver mediators of an anti-tumoral tumor microenvironment such as the interleukins (IL) IL-7, IL-15, tumor necrosis factor (TNF) and interferon-gamma (INF-γ)." (PMID 37760634, 2023). "Human OC tumour antigen-specific CD8+ T lymphocytes that co-express programmed death 1 (PD-1) and LAG-3 produce less interferon-gamma (IFNγ) and TNFα than single-positive cells." (PMID 37760841, 2023). "Vactosertib increased immune effectors (IFNγ+CD8+ cells and NK cells) and inhibited immune suppressors (M2-like TAM, MDSC) in the OS tumor microenvironment." (PMID 37066414, 2023). "Other studies further support the importance of tumor cell-intrinsic alterations driving CAR-T resistance and have highlighted an important role for IFNγ, but the mechanism appears to vary depending on the context." (PMID 38052854, 2023). "Invitro transfection with 4-1BBL/IL-12/IFNγ NPs led torobust increases in MHC-I and MHC-II expression due to local productionof IFNγ by the tumor cells themselves." (PMID 37797944, 2023). "The expressions of cytokines, IFNγ, granzyme B (GZMB), and IL-2 in the sorted T cells are attenuated in the CAP-treated mice, indicating that the functions and activities of tumor-infiltrating T cells are impaired by CAP treatment." (PMID 37189453, 2023).
tumor (continued). "OE-S-2HG-treated OT-I cells significantly increased the percentage and the expression of the cytokine interferon γ (IFNγ) after OVA restimulation, which implies that the tumor-infiltrated OT-I cells had decreased anergy." (PMID 37632752, 2023). "Interferon gamma (IFN-γ), lipopolysaccharide (LPS), and GM-CSF are important factors that regulate TAM (M1) polarization with tumor-killing cytotoxicity." (PMID 37542283, 2023). "Consistent with previous reports in murine tumors, high NOS2 expression requires IFNγ and TNFα/IL1, which exhibit a striking difference in cytokines produced during induction of murine macrophages and tumor cells." (PMID 37169743, 2023). "Abrogating HCAR1-mediated lactate signaling sensitized tumors to anti-PD-1 and metformin treatment, leading to reduced tumor volume and increased CD8+ T cell infiltration and IFNg production." (PMID 37842241, 2023). "Like IFNγ, the anti–VEGF-ANG2 antibody upregulates immune inhibitory molecules such as PD-L1 on both ECs and tumor cells to promote T-cell exhaustion, highlighting the benefit of co-treatment with anti–PD-1 antibody." (PMID 37727791, 2023). "In the repressed tumor tissue in Gpr68-/- male mice, higher percentage of CD8+ T and NK cells were observed with a higher level of IFNγ expression." (PMID 37350933, 2023). "In summary, tumor cell-derived chemokines and cytokines, such as CXCL1/CXCL8 and SRF, recruit MDSCs, TAMs, Treg and Tex, and interact with target genes, like MIF and IFNG." (PMID 37940972, 2023). "The secretion of cytokines, such as interleukin-2 (IL-2), tumor necrosis factor alpha (TNF-α), interferon-gamma (IFN-γ), and cytolytic granules, such as granzyme B (GB), are the main functional attributes of CD8+ T cells that exhibit anti-tumor activity." (PMID 36798119, 2023). "Through co-culturing tumor cells with CAR-T cells, they found that deletion of downstream genes in IFNγ signal pathway downstream genes such as IFNGR1, JAK1, or JAK2 make GBM and other solid tumors more resistant to CAR-T cell killing in vitro and in vivo." (PMID 37427373, 2023). "Tumor-specific CD8+ T cells were shown to more frequently infiltrate the TME; highly express a myriad of activation markers, including IFNg, CD44, CD69, and CXCR3; and were more efficient at directly killing cancer cells when treated with radiation + PD1-IL2v." (PMID 37979032, 2023). "IFNγ-naïve YUMM2.1 cells were implanted subcutaneously, and subsequently tumour-bearing mice received two doses of α-PD-1 antibodies three days apart." (PMID 37752135, 2023). "REP TILs were able to respond to activation in the presence of tumor cells; increases in the CD3+ (median 0.72% vs. 1.33%, P = 0.098) and CD4+ (0.46% vs. 1.08%, P = 0.012) T cell IFNγ and TNFα expressions were observed after 6 hours of co-culture." (PMID 37484198, 2023). "Overall, these conflicting reports highlight the complexity and context-dependence of the relationship between tumor intrinsic alterations and CAR-T resistance, especially when it comes to IFNγ pathway signaling." (PMID 38052854, 2023). "Studies from cancer found that CD8+ T cells can exert their tumor suppressive effects by secreting interferon-gamma (IFNγ) to mediate the downregulation of SLC7A11(Recombinant Solute Carrier Family 7, Member 11)-triggered ferroptosis in tumor cells." (PMID 38127902, 2023). "M2-type TAMs inhibit the expression of interferon-gamma (IFN-γ) and tumor necrosis alpha (TNF-α), two antitumor cytokines that exert inhibitory effects on tumor proliferation." (PMID 37753074, 2023). "IL-21 released by IL-1β-stimulated TH9 cells induced IFNγ secretion from CD8 and NK cells in tumor-bearing mice, resulting in tumor growth inhibition." (PMID 37189417, 2023). "PD-L1 expression in tumor cells correlated with CD8 + T cells and macrophages in the TME and IFN-γ expression with suppressive CTLA4+/IFNγ+ immune cells in the TME and LN." (PMID 36979688, 2023).
tumor (continued). "These pathways contribute to the response to Interferon-gamma, alpha interferon proteins, tumor necrosis factor, transplant rejection, inflammatory response, and KRAS17, indicating a higher level of tumor immune response in the ICD-high subgroup." (PMID 37587188, 2023). "In agreement with the less exhaustion and apoptosis, tumor infiltrating TCR-JUN T cells produced nearly 2-folds of IL-2 and IFNγ." (PMID 37215108, 2023). "In the presence of inflammatory cytokines such as interferon-gamma (IFN-γ) and tumor necrosis factor-alpha (TNFα), the BBB vasculature at the local tumor site becomes “activated”, leading to upregulation of PDL1/2 ligands that increase T cell exhaustion." (PMID 37345193, 2023). "It seems that CD8+ lymphocyte and CD4+ lymphocyte, as well as interferon-gamma (IFN-γ), perform a significant function in tumor antigen identification." (PMID 38021696, 2023). "The analysis was further extended to compare T cells at week 1 and 4 of tumor growth i.e., before and after TLT-1/vehicle injections in mice, which further confirmed the decrease in effector (IFNγ-producing) CD8 T cells in TLT-1–injected mice." (PMID 36305874, 2023). "In tumor-dLN, there was an increased frequency of resident CD4+ T cells and enhanced IFNγ and IFNγ+ TNF producing CD8+ and CD4+ T cells in mice with macrophage-specific PP2AcKO." (PMID 36757811, 2023). "Although, CD3+ cells, CD4+ T cells, CD8+ T cells in rIL‐1α treated group were not higher compared to saline and Blank_CPH:SA MPs, there were significantly higher IFNγ+ CD8+ T cells, which explains the observed anti‐tumor response in rIL‐1α treated mice." (PMID 37206237, 2023). "Meanwhile, the numbers of CD8+ T cells, proliferated CD8+ T cells, and activated CD8+CD69+ T cells, CD8+IFNγ+ T cells and CD8+GzmB+ T cells were the highest in tumor tissues of R848@M2pep-MPsAFP and anti-PD-1 antibody-treated group." (PMID 37704614, 2023). "In vitro experiments with oncolytic reovirus showed that DCs loaded with infected tumor cells secreted NK chemotactic factors and induced CD69 upregulation and IFNγ expression in NK cells, which in turn promoted DC maturation." (PMID 36765035, 2023). "Following tumor cell recognition via IFNγ ELISPOT, we also tested in vitro cytotoxic effects of TCR-transduced T cells on tumor cells." (PMID 36969213, 2023). "It has been demonstrated that IL-12, through the IFNg-IDO axis, can lead to regulatory T cell (Treg) rebound suppression and tumor escape." (PMID 37190138, 2023). "The PRF1 cluster also upregulated Th1 markers IFNG and CXCL13, which contribute to tumor control by up-regulating HLA-II and promoting the formation of tertiary lymphoid structures (TLS), respectively." (PMID 37185301, 2023). "Within the tumor microenvironment, we found that inhibition of TLR1/2 by the small molecule CU-CPT22 dramatically decreased the effect of OXP, leading to fewer tumor-infiltrating immune cells, including CD4+, CD8+ and IFNγ+ CD8+ cells." (PMID 37945630, 2023). "It was also recently determined that CTLs secrete IFNγ to activate the STAT1-IRF1 axis, in order to repress the expression of SLC7A11 and SLC3A2 to induce the extrinsic ferroptosis pathway in tumor cells." (PMID 36672246, 2023). "These 2D simulations comprise tumor cells, IFNγ-secreting CD8+ T cells, and a partial differential equation (PDE) layer describing the spatiotemporal spreading of IFNγ." (PMID 37638024, 2023). "The prominent role of IFNα/β, IFNγ and TNFα pathways in the induction of antigen processing and MHC-I-mediated antigen presentation on tumor cells prompted us to test H2Kb-OVA expression in CTRL and Adam2 O/E cells in response to IFNβ, IFNγ and TNFα treatment." (PMID 37258521, 2023). "In the TME, programmed death-ligand 1 (PD-L1) expression on cancer cells is mainly regulated by Interferon-gamma (IFN-γ), which induces T cell exhaustion and enables tumor immune evasion." (PMID 38102680, 2023).
tumor (continued). "Particularly, we found that RT- and IFNγ-pretreated A549 significantly induced higher CD8+ T cell activation compared to untreated A549 cells, resulting in higher anti-tumor immunologic activity by measurement of A549 colony formation." (PMID 36688994, 2023). "Olaparib and atezolimumab (anti-PD-L1) increased IFNγ, TNFα, and CXCL9/CXCL10 expression and tumor infiltration by lymphocytes." (PMID 36831435, 2023). "The first one constructed chimeric antigen receptor T (CAR-T) cells targeting KIT in 2013, and then demonstrated that such cells were able to produce IFNγ in vitro, lysed the cultured GIST cells and inhibit tumor growth in CDX model." (PMID 37072770, 2023). "We explored the effects of IFNγ preconditioning and PARP14 depletion on the composition and activation status of the tumour immune infiltrate." (PMID 37752135, 2023). "In particular, both IFNγ and IFN-α signalling pathways were upregulated significantly in the α-PD-1-relapsing tumour." (PMID 37752135, 2023). "PKM2 knockout (PKM2KO) T cells following co-culture with HKP1-ova-GFP tumor cells showed higher levels SlamF6 and TCF1 with concomitant decreases in GzmB, IFNγ, and TNFa." (PMID 37790365, 2023). "Classically activated macrophages, also termed M1 macrophages, are stimulated by molecules such as LPS, interferon-gamma (IFN-γ), tumor necrosis factor-alpha (TNF-α), and GM-CSF, as well as by target pathogens and tumor cells." (PMID 36831623, 2023). "Macrophages that ingested glucose can develop into M1 macrophages after receiving interferon gamma (IFN-γ) secreted by Th1 cells, and the anti-tumor ability of M1-macrophages can be enhanced." (PMID 37663261, 2023). "EZH2 inhibition, a histone-lysine N-methyltransferase, has reported to suppress anti-tumour immunity by driving MDSC differentiation from primitive hematopoietic progenitors reducing CD4+ and IFNγ+CD8+ T cells in lung and colon carcinoma models." (PMID 36161514, 2023). "This confirmed the rationale for combining therapies: oncolytic vaccinia to increase tumor-infiltrating T cells, dnTGFβmm to reduce TME suppression, and αPD-1 to improve the anti-tumor T cell response and increase intratumoral IFNγ." (PMID 37552475, 2023). "Interferon-gamma (IFN-γ), commonly referred to as type II interferon, is a crucial cytokine that coordinates the tumor immune process and has received considerable attention in tumor immunotherapy research." (PMID 37646041, 2023). "This method alone decreased tumor volume and increased CD8+ T cell production of IFNg and, together with anti-PD-1, elicited a more robust anti-tumor effect in murine mammary carcinoma tumors." (PMID 37842241, 2023). "The IFNγ levels for T-mfIL12 were significantly higher than those for T-mIL12-IRES both in the tumor and serum on day 1 (p = 0.014 and p = 0.027, tumor and serum, respectively, one-way ANOVA)." (PMID 36966232, 2023). "IFNγ and TNF-α are pleiotropic cytokines with both anti- and pro-tumoral effects, depending on context and elements in the tumour microenvironment (Waters, Pober, and Bradley, 2013a; Waters, Pober, and Bradley, 2013b; Gocher, Workman, and Vignali, 2022)." (PMID 37346794, 2023). "After co-culture with IFNγ pre-stimulated MC38-L cells, Rpl18-TCR transduced T cells also showed tumor recognition." (PMID 36969213, 2023). "Another biomarker of anti-PD-1 therapies efficacy is based on the expression of PD-L1 on tumor cells, which is induced in response to CD8 TILs activation and IFNγ production." (PMID 37370739, 2023). "Collectively, these results suggest that ANGPTL2 suppresses IFNγ‐induced MHC‐I expression and intracellular MHC‐I antigen processing to attenuate antigen‐specific T‐cell activation and killing of tumor cells." (PMID 37452654, 2023). "This revealed that MSI and MSS CRC had highly distinct tumor-reactive signaling and TCR specificities within the IFNG+CD8+ T cell compartment." (PMID 37968259, 2023).